CASP8 (caspase 8)
Diseases named in the same sentence as CASP8 in open-access papers (continued):
Sharing a sentence is not in itself a finding about the gene and the disease.
breast carcinoma (continued). "To interrogate, whether this effect may also apply to malignant breast cancer tissue, we quantified Caspase 8 mRNA expression in 55 breast cancer patients from which snap-frozen cancer tissue for RNA-extraction was available." (PMID 27507139, 2016). "This is the first report, showing negative and independent prognostic impact of the CASP8 -652 6N Del and the 302His variant for breast cancer." (PMID 27507139, 2016). "Subsequently, we investigated, whether CASP8 -652 6N InsDel genotyping may provide prognostically relevant information for breast cancer patients." (PMID 27507139, 2016). "Moreover, the death receptor pathway, with caspase 8 as key regulator, was shown to be de-regulated in malignant tumor cells, such as in breast cancer cells, in dysplastic cells or in carcinomas in situ." (PMID 27507139, 2016). "Given the important role of caspase-8 in apoptosis, we hypothesized that additional CASP8 polymorphisms would be associated with breast cancer risk and that the associations might be specific to some breast cancer subtypes." (PMID 26758508, 2016). "In conclusion, we revealed the CASP8 -652 deletion variant to be an allele-dose dependent negative prognostic factor for patients with breast cancer." (PMID 27507139, 2016). "In conclusion, we revealed the CASP8 Asp302His variant to be an allele-dose dependent and negative prognostic factor for patients with breast cancer." (PMID 27507139, 2016). "There is no known functional effect of CASP8-rs1045485, however, it is associated with a risk haplotype in CASP8, which is more strongly associated with breast cancer risk." (PMID 23544014, 2013). "CASP8 and maspin expression were reduced in breast cancer cells due to promoter methylation." (PMID 20132554, 2010). "In conclusion, our results show that methylation of CpG sites at the promoter region in certain genes, such as CASP8 and maspin, could result in transcriptional downregulation or silencing of genes and protein in breast cancer cells." (PMID 20132554, 2010). "We examined if 5-Fu treatment could upregulate CASP8 in breast cancer and if the upregulation involved demethylating CpG sites on CASP8 promoter." (PMID 20132554, 2010). "CASP8 mRNA was undetectable in MCF-7 breast cancer cells due to promoter methylation." (PMID 20132554, 2010). "Despite success in identifying CASP8, candidate gene approaches have not been widely successful in identifying additional breast cancer susceptibility genes." (PMID 21037853, 2010). "Interestingly, in presence of downregulated levels of XIAP, there is an accumulation of the cleaved p43 and p41 forms of caspase-8, both in melanoma and mammary carcinoma cell lines." (PMID 20461078, 2010). "Taken together, our results confirm that expression of CASP8 in breast cancer is epigenetically controlled and the modification may vary in different types of breast cancer cells." (PMID 20132554, 2010). "BCAC also analyzed data from 12 studies for 16 SNPs in various candidate genes and concluded that only 5 SNPS (CASP8 D302H, IGFBP3-202 c > a, PGRV660L, SOD2 V16A, and TGFB1 L10P) were associated with breast cancer, but the statistical significance of the association was only borderline." (PMID 21655367, 2008). "In the replication stage of MR, CASP8 continued to show a negative correlation with breast cancer risk (IVW: OR = 0.75, 95% CI: 0.62-0.89, P = 0.001), and DDX58 maintained an inverse association with breast cancer risk (IVW: OR = 0.80, 95% CI: 0.67-0.94, P = 0.007)." (PMID 39351539, 2024). "Also, IGFBP-3 activates Caspase-8 cleavage and induce apoptosis in breast cancer." (PMID 39272080, 2024). "Furthermore, CASP8 (2%), NLRC4 (1%), NLRP3 (1%), NLRP2 (1%), PLCG1 (1%), NLRP1 (1%), NLRP7 (1%), SCAF11 (1%), GSDMC (1%), and NOD1 (1%) occurred somatic mutations as well as most of them had high frequencies of CNV in breast cancer." (PMID 34589498, 2021). "Hence, we examined the role of caspase-8 in TRAIL-induced IFN signaling in breast cancer cells." (PMID 33770100, 2021).
breast carcinoma (continued). "Thus, RCC2 and CASP8 were considered as protective factors in breast cancer." (PMID 33170908, 2020). "However, a generally lowered caspase 8 mediated apoptotic threshold does not seem to be tumor promoting in existing breast cancer, since we clearly show that the -652Del allele in patients with already existing breast cancer is prognostically favorable." (PMID 31467295, 2019). "Therefore, we may hypothesize that both polymorphisms may account for an additive or even synergistic effect on total caspase 8 activity in breast cancer cells." (PMID 27507139, 2016). "Thus, we presume that CDDO-Me–induced downregulation of c-FLIPL, a caspase-8 inhibitor, may help tip the balance towards caspase-mediated apoptotic cell death in breast cancer cells undergoing progressive ER dilation." (PMID 26053096, 2015). "Thus, IRF-1 controls apoptosis through caspase-8 in breast cancer cells." (PMID 23420765, 2013). "Our study further found that ABL-N induced significant activation of caspase-8 in the breast cancer cells, suggesting that ABL-N may activate the death receptor pathway and induce the expression of death receptors or death ligands such as tumor necrosis factor-α and Fas ligand." (PMID 20096139, 2010). "Thus, we further investigated whether 5-aza-dc reduces histone H3 methylation to activate CASP8 transcription in breast cancer cells." (PMID 20132554, 2010). "To further confirm our hypothesis that loss of CASP8 in breast cancer cells may be due to promoter methylation, we performed MSP, which detected methylation of CpG sites of CASP8 in 5-aza-dc untreated breast cancer cells, MCF-7, MB231, SKBR3, and HCC1937 but not in MCF10." (PMID 20132554, 2010). "LY01005, a GnRH agonist currently in clinical trials, aims to reduce estrogen levels, while Everolimus, an mTOR inhibitor, exerts anti-breast cancer effects through inhibition of the PI3K/Akt/mTOR pathway and activation of caspase-8-mediated apoptosis." (PMID 40649817, 2025). "In the MCF-7 breast cancer cell line, DOX treatment leads to increased BAX expression, elevated levels of caspase-8 and caspase-3, and decreased BCL-2 expression." (PMID 40530298, 2025). "CASP8, DDX58, CPNE1, ULK3, PARK7, and TNFRSF9 have already been identified as targets in drug development and potential therapeutic targets for breast cancer treatment." (PMID 39351539, 2024). "It has also been reported that in vitro experiments, lentiviral particles Gag-CASP8-VLPs, carrying activated caspase-8 and constructed using the VSV G protein (VSV-G) as the vector, can enter breast cancer cells and inhibit tumor cell growth." (PMID 39003473, 2024). "Total findings concluded that PARP cleavage, CYCS releasing, caspase-8, and enhanced expression of FADD authenticates the A. fragrantissima induces apoptosis in breast cancer MCF-7 cells." (PMID 38820323, 2024). "In breast cancer cells, anticancer drug treatment activates the extrinsic pathway via DR4/5 and Fas-mediated caspase-8, which, in combination with the activation of the intrinsic pathway by Bax induction, Cyt c release, and caspase cascade, leads to apoptosis." (PMID 38473345, 2024). "Oleocanthal induces apoptosis via activation of caspase-8, -9 and -3 followed by the cleavage of poly(ADP-ribose) polymerase (PARP) in hepatocellular carcinoma, hematopoietic tumor cells, and breast cancer." (PMID 39203892, 2024). "At least three genes from this list were involved in the formation of carcinomas, including breast carcinoma (CASP8, HSPA4, BCL2L11), prostate carcinoma (BCL2, CASP8, BCL2L11, ATM), and chronic lymphocytic leukemia (BCL2, CASP8, FAS, BCL2L11, BAK1)." (PMID 37298337, 2023). "On the contrary, quercetin triggered a caspase-dependent extrinsic apoptosis by upregulating caspase-8 and -3 and parp-1 cleaved forms in BT474 human breast cancer cells." (PMID 36675194, 2023). "Hence, promoting CASP8 expression might help well in the treatment of breast cancer." (PMID 38081857, 2023).
breast carcinoma (continued). "Ultimately, caspase-8 cleaves GSDMC to generate GSDMC-NTD, inducing pyroptosis in breast cancer cells." (PMID 37781519, 2023). "For CASP3 and CASP8, the greatest increase occurred after treatment with M and MGO breast cancer tumors." (PMID 37176095, 2023). "All four genes identified by PrediXcan only were located near breast cancer SNPs previously identified by GWAS11, and three genes (CASP8, ALS2CR12, and STXBP4) also were reported by prior breast cancer TWAS 15,32." (PMID 36690614, 2023). "Both arsenic compounds upregulate expression levels of antiapoptotic genes BCL2 and BCL2L1 and downregulate expression levels of proapoptotic genes CASP8 and CASP9, promoting apoptosis in breast cancer cells." (PMID 36619302, 2022). "It has been demonstrated that silybin stimulated under-expression of Bcl-2 and overexpression of Bax and Casp-8, Casp-9, and BID in MCF-7 breast cancer cells." (PMID 34094034, 2021). "Western blotting results showed that treatment of breast cancer cells with VALD-3 resulted in cleavage/activation of cytochrome c, caspase-8, caspase-3 and PARP." (PMID 34294779, 2021). "Costunolide treatment led to the activation of Fas, caspase-8, caspase-3, and PARP cleavage in the human breast cancer cell line MDA-MD-231." (PMID 33669832, 2021). "In a study investigating the influence of DOX on apoptosis in breast cancer cell lines, DOX upregulated Bax, caspase-8 and caspase-3 expressions while downregulating the anti-apoptotic Bcl2 and Bcl-xL levels." (PMID 33750916, 2021). "Caspase-8 induced the opening of the GSDMC-NT pore on the cell membrane, leading to pyroptosis in breast cancer cells." (PMID 33634141, 2021). "Research has shown that in human breast cancer MCF-7 cells and PC-3 prostate cells, narciclasine can activate Caspase-8 and Caspase-10 receptor pathways and induce apoptosis of tumor cells." (PMID 34753517, 2021). "For example, CUL7 promotes the survival of a variety of cancer cells, including MDA-MB-231 breast cancer cells, HeLa cells and HEK293T cells, by promoting caspase-8 ubiquitination." (PMID 32252802, 2020). "In a later study we detected activated caspase-8 24 h after serum withdrawal in breast cancer cells and noticed that treatment with FVIIa reduced the formation of the death inducing signaling complex (DISC) responsible for caspase-8 activation." (PMID 32458278, 2020). "Subsequently, we correlated CASP8 -652 InsDel genotypes with the patients’ clinicopathological data, including hormone receptor and HER2-receptor status and the intrinsic breast cancer subtype." (PMID 31467295, 2019). "In the present study, we observed a favorable influence of the CASP8 -652Del and the 302HisHis genotype on DFS in early breast cancer and reported that the 302HisHis genotype correlates with low TIL concentration." (PMID 31467295, 2019). "In breast cancer cells, selective suppression of FLIP expression by RNA interference induces caspase-8-dependent apoptosis both in vitro and in vivo." (PMID 29212182, 2017). "Our findings are corroborated by breast cancer patient data, showing that high expression of miRNA-519a-3p and low coexpression of the target genes CASP7, CASP8 and TNFRSF10B correlate with poor relapse-free survival in breast cancer patients." (PMID 28771222, 2017). "We show that miR-519a-3p indeed leads to inhibition of TRAIL- and FasL-induced apoptosis in breast cancer cell lines by directly targeting the proapoptotic TNFRSF10B (TRAIL-R2) and CASP8 (caspase-8) mRNAs." (PMID 28771222, 2017). "Our data also showed that cleaved caspase-3, caspase-8, caspase-9 and poly ADP ribose polymerase-1 (PARP-1) were all increased in breast cancer cells." (PMID 28060760, 2017). "Here, we analyzed the impact of the expression of direct and indirect miR-519a-3p target genes CASP8, TNFRSF10B and CASP-7 on the clinical outcome using published breast cancer data sets." (PMID 28771222, 2017).
breast carcinoma (continued). "A recent study detected a dramatic decrease in cell proliferation, as well as significant stimulation of apoptosis signaling pathways, such as PARP cleavage and caspase-8 and -9 cleavages in apigenin-treated SKBR3 breast cancer cells." (PMID 27657126, 2016). "However, although breast cancer was primarily adressed by recent CASP8 -652 6N Del and CASP8 Asp302His susceptibility studies, surprisingly, prognostic relevance of these caspase 8 polymorphisms has not been investigated in breast cancer so far." (PMID 27507139, 2016). "Thus, we may conclude that the CASP8 -652 6N Del or the CASP8 Asp302His variant provide an allele-dose dependent and negative prognostic factor for breast cancer, independently from each other." (PMID 27507139, 2016). "In human breast cancer cells, the ubiquitin-binding protein SQSTM1/p62 and LC3B interact with caspase-8 to promote caspase-8 oligomerization, activation, and apoptosis." (PMID 23691463, 2012). "In breast cancer cells MCF-7, the cytotoxic effect of somatostatin is dependent on SHP-1 and results from caspase 8 activation, cell acidification and mitochondrial dysfunction." (PMID 21143993, 2010). "However, the apoptosis-related genes TRAIL-R2 (TNFRSF10B) and caspase-8 (CASP8] are targeted and inhibited by the oncogenic miR-519a-3p, which is highly expressed in breast cancer." (PMID 41614928, 2026). "According to these predictions, the mechanism of SA in breast cancer may involve the regulation of several proteins, including cytochrome enzymes (CYP1A1 and CYP3A4), PRKCA, CASP8, SIRT1, and CTNNB1." (PMID 40427522, 2025). "The association of hepatocyte growth factor (HGF) with breast cancer was stronger in Estrogen Receptor (ER)-negative patients, while CASP8, CXCL11, MMP7, and C–C motif chemokine 4 (CCL4) were associated with ER-positive breast cancer." (PMID 40665092, 2025). "Notably, proteins such as CASP8 and DDX58, which are already targeted for other diseases, exhibit promising potential as novel therapeutic targets for breast cancer." (PMID 39351539, 2024). "Moreover, administration of EPZ in breast carcinoma BT549, glioblastoma U87 and colon carcinoma HT29 cells led to the decrease in CD95L-induced caspase-8 and caspase-3/7 activities." (PMID 38730267, 2024). "In addition, CASP8 and CTNNB1 managed to be in the top 3 lead hits identified via network pharmacology; CASP8 is found to be down-regulated in breast cancer due to promoter methylation." (PMID 38081857, 2023). "Additional evidence for the interesting results outlined in this recent paper has also been reported by Syamet al.70 that showed apoptosis induction in breast cancer (MCF7) through stimulating the production of caspase-7, caspase-8, and caspase-9 using synthesized chalcone derivatives." (PMID 38110432, 2023). "It was confirmed by the analysis in Annexin V binding assay, as well as our observation of the increased caspase-8 and caspase-9 concentrations and decreased mitochondrial membrane potential in comparison with the untreated control in both MCF-7 and MDA-MB-231 breast cancer cells." (PMID 35456915, 2022). "Our results are in line with another study which demonstrated that honey induces intrinsic or caspase-9 apoptotic pathway in breast cancer with no evident involvement of caspase-8 pathway." (PMID 35386216, 2022). "For example, while the upregulation of GSDMC is cleaved by caspase-8 and induces pyroptosis in MDA-MB-231 and BT549 breast cancer cells, knockdown of GSDMC significantly inhibits proliferation and tumorigenesis in colorectal cancer in a pyroptosis-independent manner." (PMID 35990696, 2022). "The expression of key markers associated with proliferation (MKI67, PCNA, CCNB1, MYBL2, BUB1, CCND1), apoptosis (BCL2, CASP7, CASP8, CASP9, CASP3, BAX, APAF1), differentiation (CDH1, CD24, EPCAM, ESR1, NGFR, RUNX1), and breast cancer stemness (CD44, ITGA6, DNER, ALDH1A3, ABCG2, PROCR) was assessed." (PMID 35183258, 2022).
breast carcinoma (continued). "Thus, the role of caspase 8 in celecoxib-induced apoptosis in human lung cancer cells was shown, whereas apoptosis induced by another NSAID (FR122047) in MCF-7 breast cancer cells was even enhanced by siRNA knockdown of caspase-9." (PMID 33807213, 2021). "Compared with the control group, the levels of cleaved Caspase-3, cleaved Caspase-8 and cleaved PARP were significantly increased in VALD-3-treated breast cancer cells, indicating that VALD-3 could simultaneously activate these proteins." (PMID 34294779, 2021). "For example, an EPA-enriched fraction from the diatom Cocconeis scutellum Ehrenberg (Bacillariophyceae) had antiproliferative activity on breast carcinoma (BT20) cells, with activation of caspase-3 and caspase-8, and cell cycle progression block from S to G2-M phases." (PMID 33922258, 2021). "In breast cancer cells, quercetin induced caspase-dependent extrinsic apoptosis by up-regulating the levels of cleaved caspase-8 and caspase-3 without altering the mitochondrial membrane potential." (PMID 31366565, 2019). "Moreover, we also found clear reporter cleavage showing granzyme B and caspase-8 activity in HeLa and MDA-MB-468 breast carcinoma cells with activated primary NK cells as effector cells." (PMID 30135688, 2018). "Previous investigations had reported that TSC2, ARID1A, AXIN1, CASP8, CDH1, and ASXL1 could play roles in tumor suppression in diverse cancer types, including breast cancer." (PMID 29414922, 2018). "The mechanism by which the antisense SVA insertion results in decreased CASP8 expression in breast cancer is unclear but it is not thought to be due to aberrant splicing." (PMID 27158268, 2016). "We conclude that the CASP8 SNP, rs2293554, is nominally statistically significantly associated with HER2-positive breast cancer risk in non-Hispanic white women, even after stringent correction for multiple comparisons." (PMID 26758508, 2016). "Collectively, apoptotic data suggest that simvastatin induces apoptosis through both enhancing the activities of caspase-3/7 and promoting the cleavage of caspase-8, caspase-3 and PARP in some breast cancer cells; caspase-3 appears to be a major caspase involved in simvastatin induced apoptosis." (PMID 26565813, 2016). "This study is the first to identify the CASP8 SNP, rs2293554, to be statistically significantly associated with HER2-positive breast cancer risk in non-Hispanic white women." (PMID 26758508, 2016). "Lactoferricin, a peptide derived from lactoferrin has also demonstrated increased apoptosis via the intrinsic pathway in leukemic and breast carcinoma cells by activating caspases-3 and -9 but not caspase-8." (PMID 25998617, 2015). "The authors have described G2/M arrest, activation of caspase-9 and caspase-3/7 (but not caspase-8) in the metastatic breast cancer cell line MDA-MB-231 by boldine, which also down-regulates Bcl-2 and heat shock protein 70 and up-regulates Bax." (PMID 25719742, 2015). "In addition to the influence of selenium on caspase activation, it also promotes apoptosis by increasing Fas-associated death domain (FADD) expression and enhancement of caspase-8 recruitment for Fas and FADD (MCF7 breast cancer)." (PMID 25821636, 2015). "The mRNA levels of CASP8 and maspin were lower in breast cancer tissue than non-breast cancer tissue (data not shown)." (PMID 20132554, 2010).